MARCHF4 (membrane associated ring-CH-type finger 4)
Description:
E3 ubiquitin-protein ligase that may mediate ubiquitination of MHC-I and CD4, and promote their subsequent endocytosis and sorting to lysosomes via multivesicular bodies. E3 ubiquitin ligases accept ubiquitin from an E2 ubiquitin-conjugating enzyme in the form of a thioester and then directly transfer the ubiquitin to targeted substrates.
Synonyms: MARCH-IV; KIAA1399; MARCH4; RNF174
Tractability: Antibody: UniProt predicts a signal peptide or a membrane-spanning region.
Gene: Protein-coding gene on chromosome 2 (216,257,865 to 216,372,483, reverse strand). Ensembl gene ENSG00000144583.
Subcellular location: Golgi apparatus membrane
Gene Ontology:
Molecular function: protein binding; ubiquitin-protein transferase activity; ubiquitin protein ligase activity; zinc ion binding
Biological process: protein ubiquitination
Cellular component: Golgi stack; trans-Golgi network; Golgi membrane
Genetic constraint (gnomAD): Loss-of-function variants: 14 observed, 44.19 expected, observed/expected ratio (o/e) 0.32, 90% interval 0.21 to 0.5. The upper end of that interval is the gene's LOEUF score, 0.5, which puts it in group 2 of 6, group 1 being the genes least tolerant of losing a copy. Missense variants: 468 observed, 546.03 expected, observed/expected ratio (o/e) 0.86, 90% interval 0.79 to 0.93. Synonymous variants: 226 observed, 214.34 expected, observed/expected ratio (o/e) 1.05, 90% interval 0.94 to 1.18.
Homologues: Orthologues: chimpanzee MARCHF4 (100% identical), macaque MARCHF4 (99% identical), pig MARCHF4 (93% identical), rabbit MARCHF4 (93% identical), guinea pig MARCHF4 (92% identical), dog MARCHF4 (91% identical), mouse Marchf4 (90% identical), rat Marchf4 (90% identical), zebrafish marchf4a (57% identical), tropical clawed frog pecr (54% identical), zebrafish marchf4b (52% identical). Paralogues in human: MARCHF9 (51% identical), MARCHF11 (40% identical), MARCHF1 (19% identical), MARCHF8 (19% identical), MARCHF2 (15% identical), MARCHF3 (14% identical).
Diseases named in the same sentence as MARCHF4 in open-access papers:
MARCHF4 is named in the same sentence as 7 diseases in open-access papers, as found by Europe PMC text mining. Sharing a sentence is not in itself a finding about the gene and the disease. The quoted sentences say what the papers report.
prostate carcinoma (2 papers, 2023 to 2025). A carcinoma that arises from epithelial cells of the prostate gland. "MARCHF4 (membrane associated ring-CH-type finger 4), a member of E3 ubiquitin protein ligase, promoted viability of prostate cancer cells after mitoxantrone treatment." (PMID 36733484, 2023). "MARCHF4 overexpression caused chemotherapeutic agent resistance in prostate cancer cells." (PMID 36733484, 2023). "Overexpression of MARCHF4 induced EMT in prostate cancer cells." (PMID 36733484, 2023). "Moreover, MARCHF4, a membrane associated E3 ubiquitin ligase from the MARCH family, has previously been shown in prostate cancer cells to enhance survival under chemotherapeutic stress, promote an epithelial mesenchymal transition phenotype, and mitigate chemotherapy induced apoptosis." (PMID 40672941, 2025).
cutaneous squamous cell carcinoma (1 paper, 2021). "MARCHF4, previously known as MARCH4, was identified as a potential therapeutic target in cutaneous squamous cell carcinoma." (PMID 34722520, 2021).
lung adenocarcinoma (1 paper, 2025). A carcinoma that arises from the lung and is characterized by the presence of malignant glandular epithelial cells. "Notably, our study is the first to associate high MARCHF4 expression with adverse outcomes in lung adenocarcinoma." (PMID 40672941, 2025). "Given that LCAL1 and RHOV have been previously reported as prognostic genes, we validated the novel prognostic gene MARCHF4 via qRT-PCR, demonstrating that its expression was significantly upregulated in lung adenocarcinoma cells compared to normal lung epithelial cells." (PMID 40672941, 2025).
cancer (2 papers, 2022 to 2023). A tumor composed of atypical neoplastic, often pleomorphic cells that invade other tissues. "Although there is a limited number of literatures correlating MARCHF4 and cancer progression, our study suggest that cancer cell resistance driven by stromal cell-derived EREG, is at least partially mediated by MARCHF4 upregulated in recipient cancer cells." (PMID 36202915, 2022). "Second, we observed gene expression pattern indicative of regulations that may involve enhanced ubiquitination in cancer cells, a process mediated by upregulation of the E3 ubiquitin ligase MARCHF4." (PMID 36202915, 2022).
tumor (2 papers, 2022 to 2023). "Stromal cell-derived EREG-mediated drug resistance was partly due to MARCHF4 upregulation in recipient tumor cells." (PMID 36733484, 2023).
MARCHF4 also shares sentences with these, for which no sentence is quoted: glioma (1 paper); ovarian carcinoma (1).